CD4 (CD4 molecule)
Diseases named in the same sentence as CD4 in open-access papers (continued):
Sharing a sentence is not in itself a finding about the gene and the disease.
tumor (continued). "We used syngeneic orthotopic mouse tumour models (wild-type, NOD/scid and Nude), employed knockout (CD8 and CD4) models and administered CXCL4." (PMID 33795809, 2021). "Strong immunologic changes were observed in the blood and tumor microenvironment (TME), marked by increases in CD8+ and CD4+ T cells and NK cells." (PMID 34790830, 2021). "SNRPC expression was negatively correlated with the infiltration of CD4+ T cells, macrophage cells, and neutrophil cells (all P < 0.05), as determined by analyzing the TIMER (Tumor IMmune Estimation Resource) database." (PMID 33934562, 2021). "These cells can then actively suppress proliferation of CD4+ and CD8+ T lymphocytes that would otherwise recognize tumor antigens." (PMID 35070956, 2021). "CXCL10 is a chemokine that is involved in attracting CD4 and CD8 cells to the tumor microenvironment in a variety of tumors." (PMID 34447697, 2021). "administrated neoantigen-reactive CD4+ TILs in a patient with metastatic cholangiocarcinoma (NCT01174121), resulting in complete tumor regression." (PMID 34513673, 2021). "Analyses of data obtained from TIMER and TCGA data showed that BTBD10 was positively correlated with B cells, CD4+ T cells, CD8+ T cells, macrophages, DCs and neutrophils in the tumor." (PMID 35059434, 2021). "In the meantime, the increases in the percentages of CD4+ and CD8+ T cell, CD4+CD69+ and CD8+CD69+ T cell were found in tumor tissue and in lymph node near the tumor." (PMID 33816301, 2021). "These include an increase in CD8+ T-cells and effector memory T cells (CD44+ CD8+ CD62L+) and a decrease in Treg cells (CD4+ CD25+ Foxp3+) and M2 macrophages in the tumor microenvironment." (PMID 34360802, 2021). "Among the major tumor-infiltrating immune effector cells that can be identified by TIMER, including T cell (CD4 T cells and CD8 T cells), B cells, macrophages, neutrophils, and dendritic cells." (PMID 33790054, 2021). "When co-cultured with either 90Y-NM600-treated MOC2 or 90Y-NM600-treated B16 cells, both CD4+ T cells and CD8+ T cells demonstrated significantly increased expression of CTLA-4, as compared to those co-cultured with untreated control tumor cells." (PMID 33995649, 2021). "The quantitation of T cells by image analysis revealed that infiltration of CD4+ or CD8+ T cells was enhanced by nivolumab treatment in huNOG-FcγR−/− mice, but the degree was largely dependent on the tumor cell lines." (PMID 34702924, 2021). "For this purpose, tumor-specific CD4 and CD8 T cells were shown to increase their effector functions to slow tumor growth by increasing PEP production through the over-expression of phosphoenolpyruvate carboxykinase 1 (PCK1)." (PMID 34638609, 2021). "Since TAMs are known to regulate CD4 T cells in GBM10, we asked the relative contribution of Treg cells vs. TAMs in GBM tumor development." (PMID 33976133, 2021). "Tumor-infiltrating lymphocytes (TILs) are highly heterogeneous population which include B lymphocytes, CD8+ cytotoxic T lymphocytes, cytokine-secreting CD4+ T helper lymphocytes, and Forkhead box P3 (FoxP3)+ Tregs." (PMID 33579265, 2021). "DEGs from macrophages, CD4+ and CD8+ T cells (differential expression in tumor versus healthy tissue) were further assessed with Reactome pathway enrichment analysis." (PMID 33918618, 2021). "In NPC, a number of studies have shown a positive correlation between overall survival and tumor infiltration by CD3+, CD4+, and CD8+ T-cells." (PMID 34572108, 2021). "MT110 has been shown to induce synergistic stimulation of CD4- and CD8-positive T cells and to reactivate tumor-resident T cells to eradicate tumor cells." (PMID 34922633, 2021). "For tumor-infiltrating lymphocytes (TILs), subgroup analysis demonstrated FOXP3 and PD-1, PD-L1, lymphocyte activation gene-3, CD3, CD4, or CD8 double positive were significantly correlated with longer RFS." (PMID 34006632, 2021).
tumor (continued). "Findings reveal, a positive correlation between the CD4+/CD163+ and CD8+/CD68+ T cell ratio which can be attributed to cross talking between macrophage surveillance and T cell signaling in tumor microenvironment." (PMID 34326381, 2021). "We have shown before that stable expression of CIITA in human tumor cells leads to constitutive functional expression of HLA-II, that endogenous proteins can also be directed to presentation on HLA-II complexes, and that HLA-II expressing cells may directly engage and activate CD4+ TH cells." (PMID 33592498, 2021). "One of these reports also established an opposing protumoral role for miR-146a, as evidenced by reduced tumor growth and enhanced IFN-γ production by both CD4 and CD8 T cells from miR-146a knockout tumor-bearing mice." (PMID 34830805, 2021). "The tumor tissue-infiltrated CD4+ FOXP3+ Treg were also increased after CAF depletion, which reduced tumor response to gemcitabine treatment via cytotoxic T-lymphocyte-associated protein (CTLA)-4-induced immunosuppression." (PMID 34868982, 2021). "Cellular immune responses are essential for the monitoring of malignant tumors and the control of HCC development; CD4+ and CD8+ T subtypes are identified as the primary anti-tumor immune cells." (PMID 33435880, 2021). "Immunohistochemically defined immune cell subtypes, i.e., those expressing T-cell markers (CD3, CD4 and CD8) or a B-cell marker (CD20) were characterized on tumour tissue sections." (PMID 33669038, 2021). "Seven days after adoptive transfer of CD4+ or CD8+ T cells, recipient mice were subcutaneously injected with MTT-luc cells in the right flank and were monitored for PHEO tumor development." (PMID 34439097, 2021). "Tim3 was identified as a receptor expressed on IFN‐γ‐producing CD4+ and CD8+ T cells, of which the downregulation promotes T‐cell IFN‐γ‐mediated antitumour immunity and inhibits tumour growth." (PMID 34841705, 2021). "The C57BL/6 mice bearing subcutaneous LLC or B16F10 tumor bulks were intraperitoneally injected with anti-CD8 (TIB210), anti-CD4 (GK1.5) or anti-NK1.1 (PK136) deletion mAbs respectively every 5 days from the day before the viral therapy." (PMID 33717103, 2021). "They induce target cell apoptosis and produce anti-tumour cytokines such as IFN-γ (which is involved in priming the adaptive immune system by promoting maturation of DCs and inducing differentiation of CD4+ T-cells)." (PMID 34944851, 2021). "First, we noted that the bulk of leucocytes (CD45+), including T-cells (CD4+ and CD8+), were concentrated at the periphery of tumor nodules." (PMID 33664349, 2021). "We have also demonstrated by cell deconvolution a rich and varied immune infiltration with the predominant cell types being CD4+ memory and CD8+ cells; however, M2 macrophages are seen in most tumours." (PMID 33632293, 2021). "Unlike previous reports, our aim was to provide particular focus on how tumor subsite and HPV status impacts the utility of a CD4+ CD8+ TIL biomarker in HNSCC." (PMID 33668519, 2021). "The recruitment of cytotoxic cells, namely terminally differentiated CD4+ and CD8+ T cells (TEFF), is impaired in the tumor, and the effector memory CD4+ T cells are more attracted in this region." (PMID 34869376, 2021). "In the immunohistochemical study, we observed increased CD4+ and CD8+ TILs in tumor tissues of mice treated with the combination of oral cancer vaccine and anti-PD-1 antibody." (PMID 34589578, 2021). "The experimentally induced absence of the three receptor forms of TLR (TLR 3,7,9) results in tumour regression dependent on both CD4 and CD8 T cells and protects mice from subsequent tumour provocation." (PMID 34194625, 2021). "miR-520b inhibitor enhanced CD4 and CD8 cell populations in the tumor immune microenvironment and inhibited tumor growth." (PMID 34659411, 2021).
tumor (continued). "Accordingly, the co-treatment of galunisertib with anti-PD-L1 treatment induced an immune response characterised with elevated T-bet and IFNγ levels in CD4+ T cells, increased GZMB production, along with increased infiltration into the tumours." (PMID 33669775, 2021). "We observed a significant decrease in the proportion of M2-TAMs and CD4+Fop3+ T cells, while there was a significant increase in the proportion of M1-TAMs and CD8+ T cells, and in the activity of T cells, and thus in the tumor inhibition rate." (PMID 34515617, 2021). "Tumor necrosis factor-α (TNF-α) is one of the primary proinflammatory cytokines produced by CD4+ TH1 cells and binds to two receptors, TNFR1 and TNFR2, that promote cell death and destruction of tumor vasculature." (PMID 34012451, 2021). "To date, most T cell therapeutic approaches have focused on tumor diseases using genetically engineered T cells expressing an MHC I-restricted TCR or a CAR, and those T cell products typically also include redirected CD4+ T cells." (PMID 34853796, 2021). "Based on the TIMER database, the expression of all prognostic APOBECs was negatively correlated with tumor purity while positively correlated with B cells, CD8 T cells, CD4 T cells, Macrophages, Neutrophil, and Dendritic cells." (PMID 34729111, 2021). "The model polarized macrophages to an M1-like phenotype, and this M1 activation increased proinflammatory cytokines, promoting the infiltration and activation of CD4- and CD8 T cells in the tumor microenvironment." (PMID 34852326, 2021). "We found that there were more CD4+ T lymphocytes and fewer CD15+ neutrophils in tumour tissues with low TMEM92‐AS1 expression." (PMID 33247987, 2021). "Both CD4+ and CD8+ activated lymphocytes express programmed cell death protein-1 (PD-1) with inhibitory effects after binding to specific ligands present on tumor and immune cells." (PMID 34066837, 2021). "This study showed that animals in the combination groups had a consistent trend of increased infiltrated CD4+ and CD8+ T cells, significantly decreased percentage of double-positive PD-1+ CD8+ T cells, and reduced MVD in tumor tissues." (PMID 34686154, 2021). "Compared with WT mice, the number of macrophages infiltrating the tumor of IRF3KO mice was significantly reduced, and CD4+ T cells and CD8+IFNγ+ T cells were significantly increased." (PMID 34768716, 2021). "Following this approach, we observed that the excluded phenotype was characterized by CD4+, CD8+, CD20+, and CD56+ lymphocytes that were preferentially located at the tumor border at large distances from tumor cells." (PMID 34580291, 2021). "While anti-CTLA-4 therapy acts mainly on CD4 during the antigen presentation, anti-PD-1 is more effective at restoring the effector function of exhausted CD8+ T cells to clear tumor cells." (PMID 34572799, 2021). "Intriguingly, EZH2 expression is elevated in tumor-infiltrating Tregs, and pharmacological inhibition of EZH2 destabilize FOXP3 expression and slows tumor growth through enhancement of the recruitment and function of CD8+ and CD4+ T cells." (PMID 34069564, 2021). "We also visualized the data on histograms for each tissue region to separate the CK+ (tumor/epithelial cells) and CK− (non-tumor cells), followed by CD8+ and CD4+ subsets and approximately 15,000 cells per case were analyzed." (PMID 34064871, 2021). "We also analyzed role of TPX2 in tumor immunity and found that TPX2 is involved in the infiltration of B cells, CD4+ T cells, CD8+ T cells, Macrophage cells and Neutrophils cells in OSCC." (PMID 33892811, 2021). "The changes of serum tumor markers CYFRA211, CEA, CA125 and T lymphocyte subsets CD3+, CD4+, CD8+, CD4+/CD8+ in the two groups prior to and after treatment were compared and analyzed." (PMID 34290784, 2021). "RT activates CD4+ and CD8+ T cells in the TDLN and spleen when combined with CpG+OX40 in these immunologically “cold” tumor models." (PMID 34868010, 2021).
tumor (continued). "In human cancers, human CD25 is mainly expressed on CD4+FoxP3+ Treg cells and in all tumor types studied, the level of CD25 expression in CD4+FoxP3+ Treg cells is also significantly higher than that in CD4+FoxP3− and CD8+ T cells." (PMID 34824364, 2021). "Immune cell profiling of tumor-infiltrating lymphocytes (TILs) revealed that B. bre JCM92 and B. bre Bb03 significantly increased the CD4+/Treg, CD8+/Treg, and the effector CD8+/Treg ratio." (PMID 33668827, 2021). "GITR is a therapeutic target for directly activating effector CD4 and CD8 T cells, or depleting GITR-expressing regulatory T cells (Tregs), thereby promoting anti-tumor immune responses." (PMID 33654081, 2021). "Despite a paucity of CD4+ T cell receptor (TCR) clinical studies, CD4+ T cells are primed to become important therapeutics as they help circumvent tumor antigen escape and guide multifactorial immune responses." (PMID 33542711, 2021). "In this study, we established a multiplex chromogenic immunohistochemistry (IHC) assay that allowed us to quantify the five main CD4+ T cell subsets (Th1, Th2, Th17, Tfh and Treg cells), as well as CD8+ T cells, in tumor sections from 11 NSCLC patients." (PMID 34868011, 2021). "Given that MDSCs mainly suppress the function of T cells in the tumor microenvironment, we measured the proportion of CD4+ Th1 cells and CD8+ CTLs from tumor tissue of TB mice." (PMID 33717204, 2021). "The results confirmed that CPEB3 and ACADL were significantly related to tumor immunity: CPEB3 was related to the content of B cells and neutrophil; ACADL was related to the infiltration of B cells, CD8+ T cells, CD4+ T cells, macrophages, and dendritic cells." (PMID 33719338, 2021). "In the green module, many genes were upregulated in macrophage samples from the tumor, while the same cluster of genes was partly up-regulated or down-regulated in CD4 and CD8+ T cells from the tumor." (PMID 33918618, 2021). "Tumor-infiltrating lymphocytes (TILs) are chiefly represented by T cells (CD3+) and consist of CD4+, CD8+." (PMID 34638387, 2021). "Clear evidence showed that the selective ablation of TGF-β signaling, in both CD4+ and CD8+ T cells, results in the activation of effective anti-tumor immunity in pre-clinical mouse tumor models." (PMID 33499083, 2021). "It was reported that CD4+ helper and CD8+ cytotoxic T cells exert a synergistic antitumor effect in a 1:1 ratio, positively influencing tumor eradication, and achieve high remission rates during the treatment of B-ALL patients with CD19 CAR-T cells." (PMID 34503109, 2021). "There was an inverse correlation between CD204+TAMs and CD4+TILs, in which 85% of tumours had a high expression of CD204+TAMs and a low expression of CD4+TILs." (PMID 35201470, 2021). "Overall PD-1 expression in tumour-bearing lean and obese mice was high, indicating that there was some level of exhaustion in both CD8+ and CD4+ T cells." (PMID 34445503, 2021). "Infiltration levels of macrophage M0, T cell CD4+ Th1, and T cell CD4+ Th2 were significantly upregulated in the H2AFZhigh group, indicating that the H2AFZhigh group may have a lower Th1/Th2 ratio, which is an event related to tumor immune evasion and poor prognosis of HCC." (PMID 34760688, 2021). "In the local tumor draining lymph node (TDLN), at day 3-4 post cryoablation, increased frequencies of CD8+ central memory T-cells and Foxp3+ CD4+ regulatory T-cells (Tregs) were observed only in the fast freeze group as compared to non-treated controls." (PMID 34149738, 2021). "Cancer patients with high levels of CXCL16 expression have shown more elevated levels of CD4(+) and CD8(+) tumor-infiltrating lymphocytes and NK, leading to improved disease prognosis." (PMID 34150764, 2021). "The 32 samples were also subjected to analysis of CD20, CD4, CD8, CD68, Foxp3 and P16 by multiplex immunofluorescence (mIF) staining, and the immune markers were evaluated in the tumor body (TB), tumor margin (TM) and normal stroma (NS) regions separately." (PMID 35145511, 2021).
tumor (continued). "B7-H3 expression depicts a positive correlation with the progression of tumor-node-metastasis resulting from HCC and its expression stimulates metastasis through declining the proliferative rate and IFN- γ synthesis of CD4+ and CD8+ TILs." (PMID 32902664, 2021). "Tumor-derived single-cell suspensions were stained with antibodies specific for CD45, CD3, CD4, CD8, FoxP3, NK1.1, and CD103." (PMID 34060602, 2021). "We detected strong p-STAT3 expression in tumor-infiltrating CD19+ B cells, CD4+ T cells, and CD8+ T cells only in post PARPi therapy samples but not in their counterparts before PARPi treatment." (PMID 34956861, 2021). "In the present study, inflammation-related chemokines including CCL3 and CCL4 were both increased in cSCC and AK, which helps recruit and CD4+, CD8+ T cell to kill tumor cells." (PMID 33664254, 2021). "Another key finding was the dichotomy determined between frequencies of FoxP3+ CD4+ and FoxP3+ CD4-CD8- cells in blood compared to tumor where frequencies of FoxP3+ cells were significantly higher in tissue than detected in circulation." (PMID 34926643, 2021). "Aggregates of neutrophils were often observed associated with necrotic regions within the tumour and effector cells such as CD4+ and CD8+ T cells were mostly excluded from the tumour area." (PMID 34625563, 2021). "Radiotherapy also enhances infiltration of CD4+, CD8+ T cells and cytotoxic NK into the tumor microenvironment." (PMID 34680282, 2021). "Flow cytometry analysis of 344SQ and 393P tumor tissues showed an increase in CCR5+, CCR6+, and IL-17+RORγt+ CD4+ T cells in tumors that developed resistance to therapy." (PMID 33972557, 2021). "Cancer vaccines trigger anti-tumor responses mediated by immune effectors such as cytotoxic T lymphocytes (CTLs) (CD8+T cells), CD4+T cells and antibodies against tumor cells." (PMID 34488747, 2021). "Both PD-L1 and 2 expressions on tumor cells delineate a strong positive correlation with CD3+, CD4+, CD8+, FoxP3+ cells." (PMID 32902664, 2021). "TSA-T cells primed and expanded with autologous tumor-specific peptides comprised approximately equal proportions of CD8+ (31%) and CD4+ T cells (29%)." (PMID 34795224, 2021). "Bregs can also induce the polarization of naïve CD4+T cells into both FOXP3+ Treg cells and IL-10-producing Tr1 cells, modulating cancer progression and increasing tumor metastasis." (PMID 34164398, 2021). "For those reasons, increased CD4+ and CD8+ T were observed from splenocytes analysis, while only CD8+ T cells were increased in the tumor environment." (PMID 33668827, 2021). "By categorically segregating 30 histiocytomas into 4 groups based on stage of regression, early in the regression period, CD4+ T cells out number CD8+ T cells, but as tumor regression proceeded, CD8+ T cells comprised the predominant immune cell infiltrate." (PMID 34869014, 2021). "In melanoma, HDACs inhibitors up-regulated PD-1/PD-L1 and suppressed CD4+ T cells apoptosis, which further proved the potency of HDAC inhibition in tumor immune microenvironment modulation." (PMID 34656142, 2021). "As the tumor grows, cancer cells and signal molecules in the TME recruit regulatory CD4+ T-cells (Tregs), responsible to inhibit T-cell responses, specifically priming, activation and cytotoxicity of effector immune cells." (PMID 34771694, 2021). "Since the role of T cells cannot be ignored in tumor growth and progression, we also analyzed CD4+ T cells, CD8+ cytotoxic T cells and CD4+CD25+Foxp3+ Treg cells in tumor-bearing mice." (PMID 34512367, 2021). "NK cells and CD4 T cells were also expanded over time in untreated subcutaneous SB28 tumors, indicating they are involved in tumor surveillance." (PMID 34083417, 2021). "Treg (CD4+/CD25+/Foxp3+) are immunosuppressive cells in the tumor microenvironment and correlates with tumor progression also in HCC." (PMID 34282787, 2021).